INS (insulin)
Diseases named in the same sentence as INS in open-access papers (continued):
Sharing a sentence is not in itself a finding about the gene and the disease.
diabetes (continued). "Those adults with untreated diabetes and serum glucose values greater than 100 mg/ml were very likely to have subsequently been treated with insulin, oral hypoglycemics or other drugs." (PMID 23405181, 2013). "The use of rapid-acting insulin analogues (Lispro, Aspart, Glulisine) provides lower postprandial glucose excursions in people with diabetes." (PMID 24244557, 2013). "In conclusion, our data suggest the potential use of the extract from Gelam honey in treating diabetes, by modulating the oxidative stress-induced insulin signalling pathways." (PMID 24324490, 2013). "In a person with insulin-treated diabetes, a stimulated blood C-peptide of < 0.6 nmol/l (fasting < 0.25 nmol/l and or post-meal urinary C-peptide:creatinine ratio < 0.6 nmol/mmol) are suggestive of marked insulin deficiency and Type 1 diabetes." (PMID 23413806, 2013). "Diabetes mellitus is a metabolic disorder resulting from a defect in insulin secretion, insulin action, or both." (PMID 24307994, 2013). "That’s why I know about the benefits of insulin” (3 years of insulin use/ 8 years of having diabetes)." (PMID 24164794, 2013). "Due to limited number of studies exploring diabetes patients’ experience taking insulin, our understanding about how and why patients accept insulin is still unclear." (PMID 24164794, 2013). "We will test the robustness of the model in different demographic profiles – for example, age, duration of diabetes, control of diabetes (insulin, diet or oral medication) and type of diabetes (Type I, Type II)." (PMID 23414550, 2013). "Approximately 5% of patients were converted to other regimens, whereas the remaining 5% were withdrawn from insulin therapy mainly due to improvement in diabetes control." (PMID 24011395, 2013). "In fact, those who had experienced using insulin would have improved self-efficacy and better understanding about diabetes." (PMID 24164794, 2013). "To summarize, these observations indicate that OXT and OXT analogs have potentials to improve insulin secretion to counteract glucose disorders in diabetes." (PMID 23700406, 2013). "Effect of STZ- induced (50 mg.kg−1, 8 weeks) diabetes and daily oral administration of quercetin (50 mg.kg−1) on body weight, blood glucose, serum insulin, insulin resistance (IR) index, TNF-α, C-reactive protein (CRP), systolic BP." (PMID 23717483, 2013). "They provide practical treatment connected to insulin therapy and blood glucose testing, they share the meals and exercise with the person with diabetes, and they discuss blood glucose levels and insulin titration with the person suffering from diabetes." (PMID 24455251, 2013). "Based on logistic regression models, the maximum mean daily dose of insulin in the course of treatment was associated with HOMA-IR(OR 1.9 95% CL 1.2, 3.0) after adjustment for age, prepregnancy BMI, family history of diabetes and fasting glucose." (PMID 23819910, 2013). "Despite recognising the important role of a nurse educator in insulin counselling, only a small number of diabetes nurse educators and dieticians were trained in the government sector and, when present, they had to handle heavy patient loads." (PMID 22469132, 2012). "It is interesting to remind that, in contrast to Pdx1, the sole expression of Pax4 is sufficient to reprogram alpha-cells into insulin-producing beta-cells that counter chemically induced diabetes." (PMID 23326678, 2012). "Indices of both insulin sensitivity and beta-cell function were found to be predictors, together with the glycemic levels, of diabetes development." (PMID 23185618, 2012). "In people with type 2 diabetes (the commonest form of diabetes), blood sugar control fails because the fat and muscle cells that normally respond to insulin by removing sugar from the blood become insulin resistant." (PMID 22679397, 2012). "Further, the majority of Japanese patients with type 2 diabetes mellitus are less obese and less insulin-resistant than European and American patients." (PMID 22439599, 2012).
diabetes (continued). "Insulin sensitivity showed similar marked decrease (P<0.0001) at diabetes onset, together with a tendency to continuous slow decline in the previous years." (PMID 23185618, 2012). "It is our policy to obtain an endocrinology consult in all patients who require intraoperative insulin infusions for hyperglycemia since a significant percentage of these patients are ultimately found to have diabetes mellitus." (PMID 23209941, 2012). "Diabetes is a metabolic disorder characterized by impaired endogenous insulin secretion and activity, reduced NO production and increased production of free radicals, or impaired antioxidant defenses." (PMID 22611498, 2012). "Insulin resistance is the first step in glucose intolerance and the development of type 2 diabetes mellitus, thus effective prevention strategies should also include dietary interventions to enhance insulin sensitivity." (PMID 23065486, 2012). "In this paper, we reviewed the relationship between ER stress and diabetes and how ER stress controls insulin biosynthesis." (PMID 22474424, 2012). "Further study is needed to ascertain the role of insulin and other pathological factors that are affected by increased arginase 1 expression in diabetes." (PMID 22611498, 2012). "This form of diabetes is explained by insulinopenia, which is either related to the destruction of ß cells or to a defect of insulin secretion as a consequence of the energy defect." (PMID 22284844, 2012). "Despite studies showing that strict blood glucose control decreases the incidence of secondary complications of diabetes, euglycemia is difficult to achieve with current methods of exogenous insulin replacement." (PMID 22879915, 2012). "In rodents, adipose tissue PPAR-γ mRNA and protein levels are reduced after an overnight fast in STZ-induced diabetes, which is consistent with the stimulatory effect of insulin on PPAR-γ expression." (PMID 23251156, 2012). "We already know that diabetes accelerates smooth muscle cell proliferation in atherosclerotic lesions and that it correlates with insulin levels." (PMID 22547909, 2012). "Since IRS-2 is downstream the IR for which the ligand, insulin, is markedly elevated in T2DM, our findings of higher IRS-2 in prostate cancer suggests increased risk for metastasis in men with diabetes." (PMID 23251408, 2012). "In this monogenic diabetes, pharmacologic treatment is usually inevitable; however, in spite of a frequently young age of diabetes onset, one can use a treatment alternative to insulin." (PMID 22996131, 2012). "They reported a better visual understanding of the cornerstones of diabetes self-management: food intake, insulin dosage, physical activity, and blood glucose measurements." (PMID 22868871, 2012). "These experiences related mainly to heart problems (e.g., pacemaker) and diabetes (e.g., insulin pump)." (PMID 23443394, 2012). "The course of the diabetes was labile, and despite intensive insulin therapy, the control of systemic glucose concentration was unsatisfactory." (PMID 23249420, 2012). "Nationwide surveys have shown that the prevalence of diabetes rates in Malaysia have almost doubled in the past ten years; yet diabetes control remains poor and insulin therapy is underutilized." (PMID 22469132, 2012). "Recurrent hypoglycemia (RH) is the major complication of intensive insulin treatment for diabetes mellitus." (PMID 24403983, 2012). "Insulin-treated diabetes has a poorer midterm survival and higher incidence of reoperations for mediastinitis." (PMID 22958313, 2012). "In the care of diabetes and insulin initiation, the collaboration between HCPs and the pharmaceutical industry in educational programmes and counselling for patients will eventually benefit all parties." (PMID 22545648, 2012). "Glucocorticoids exert deleterious effects on the glucose metabolism, leading to a wide range of alterations, from insulin-resistance to overt and complicated diabetes." (PMID 23316348, 2012).
diabetes (continued). "Impaired insulin secretory function plays a major role both in diabetes manifestation and progression." (PMID 22649445, 2012). "Despite continued insulin therapy advances, people with diabetes still experience a substantial frequency of hypoglycaemia and it remains a limiting factor in diabetes management." (PMID 22150786, 2012). "Although early onset manifestations of diabetes can be controlled by current oral hypoglycemic drugs or insulin treatment, serious late onset complications appear in many patients." (PMID 23304131, 2012). "During the early part of the 20th century, before insulin became available, physicians Allen and Joslin endorsed fasting and calorie-restricted diets for diabetes." (PMID 23882369, 2012). "Insulin resistance in skeletal muscle tissues and diabetes-related muscle weakness are serious pathophysiological problems of increasing medical importance." (PMID 22523676, 2012). "In diabetes mellitus, due to changes in insulin production and/or action, protein metabolism is altered." (PMID 22309804, 2012). "We found that SF induced the activation of several distinct pathways, including those involved in insulin regulation and diabetes." (PMID 22629440, 2012). "Adult neurons existing in our brain neurogenic area, such as hippocampus, have the intrinsic capacity to produce insulin, implying that adult neural stem cells have a potential as a cell source for the stem cell-based transplantation therapy of diabetes." (PMID 22988465, 2012). "The etiology of type-1 diabetes is the absolute deficiency of insulin secretion, while type 2 diabetes (DM) is a combination of resistance to insulin action and impaired insulin secretion, which accounts for more than 90% of all diabetes cases." (PMID 23259700, 2012). "Insulin tends to be used more for type I diabetes, and oral hypoglycemic agents more for type II diabetes, and the linkage between diabetes and bipolar disorder is stronger for type II than for type I diabetes." (PMID 23186328, 2012). "· Activation of both GLP-1R and GIPR is known to stimulate insulin synthesis and insulin release, and both receptors have therefore been suggested as potential targets for the treatment of diabetes." (PMID 23110768, 2012). "Diabetes usually becomes manifest when additional superimposed environmental factors supervene such as a physiological decrease in insulin sensitivity with puberty and pregnancy." (PMID 22808921, 2012). "The insulinotropic effect of GLP-1 on the pancreas has been demonstrated to be preserved in animal models of diabetes by stimulating insulin exocytosis, and promoting insulin biosynthesis." (PMID 23181056, 2012). "The clinical syndrome of glucocorticoid excess, Cushing’s syndrome, includes decreased insulin sensitivity, hyperglycemia and diabetes." (PMID 22905238, 2012). "Correspondingly, in Type 2 diabetes mellitus, skeletal muscle insulin resistance is a fundamental abnormality such that enhancement of insulin sensitivity in skeletal muscle reduces peripheral insulin resistance." (PMID 23016132, 2012). "Type 1 diabetes is more common among children and young adults and insulin injections are used for treatment, thus type 1 diabetes is also referred to as insulin dependent diabetes mellitus (IDDM) or Juvenile Diabetes." (PMID 22611498, 2012). "Within both major subgroups of diabetes there is both between individual variation and with time intra-individual reduction in a patient’s endogenous insulin secretion which results in differing treatment requirements." (PMID 22681724, 2012). "The importance of integration and collaboration between the public and private sectors, multidisciplinary teamwork and active involvement of NGOs was considered as crucial to improve service delivery for insulin initiation and diabetes care in Malaysia." (PMID 22545648, 2012).
diabetes (continued). "In line with the results obtained from the KEGG analysis, upon application of LSI analysis we found that the strongest proteomic representation for tgHD rats was significantly correlated to the energy-related terms ‘diabetes’ and ‘insulin’." (PMID 23094041, 2012). "Trigonelline also is one of the main components of Mirabilis jalapa L. root which possesses both potential insulin sensitivity and hypoglycemic and hypolipidemic effects on diabetes." (PMID 23304193, 2012). "Diabetes mellitus is characterized by abnormalities in carbohydrate, lipid and protein metabolism due to complete or relative insufficiency of insulin secretion from pancreatic β-cells and/or defect in insulin action." (PMID 24250556, 2012). "In the early 1990s the landmark Diabetes Control and Complications Trial (DCCT,) and the Stockholm Diabetes Intervention study clearly indicated that intensive insulin treatment can reduce the long-term complications of type 1 diabetes." (PMID 24278682, 2012). "In diabetic patients, topical insulin cream markedly improved wound healing, representing an attractive and cost-free method for treating this devastating complication of diabetes." (PMID 22662132, 2012). "More qualitative research is needed to increase the insight into perspectives of SMBG in insulin-treated patients with diabetes." (PMID 22397638, 2012). "Insulin allergy, although less common since the introduction of human insulin, is still an issue in the management of diabetes." (PMID 22937994, 2012). "There is abundant evidence, for future diabetes management and therapy, that safe control of the blood glucose level is vital for good diabetes management and insulin therapy." (PMID 23612026, 2012). "It is reported that SG and DJB for the treatment of type 2 diabetes in obese patients are effective treatments for diabetes, and they restore normal concentrations of plasma glucose, insulin, and glycosylated hemoglobin in 80% to 100% of patients." (PMID 22686706, 2012). "This is a considerable challenge in insulin therapy as failure of glucagon counterregulation during hypoglycemia is a key factor limiting insulin treatment in patients with diabetes." (PMID 23316165, 2012). "Nowadays, although the major agents used for diabetes treatment are synthetic drugs and insulin, they usually come with considerable side effects, such as hypoglycemia, drug-resistance, dropsy, and weight gain." (PMID 22734822, 2012). "From studies in transgenic mice that overexpress or are deficient in p27 it is concluded that this inhibitor contributes to β-cells failure during the development of diabetes in mice that are insulin resistant." (PMID 24893199, 2012). "A 76 year-old female patient with history of diabetes, hypertension and hyperlipidemia presented with flank pain after using insulin Levemir as part of her management." (PMID 22870179, 2012). "Following inactivation of c-myc overexpression insulin-producing cells regenerate and diabetes is reversed." (PMID 23326678, 2012). "Visual impression and consultations based on reflection in action seemed to have a startling effect on self-reported perception of the coherence of the cornerstones of diabetes treatment: diet, insulin dosage, physical activity, and blood glucose measurements." (PMID 22868871, 2012). "Recent experimental studies demonstrate that insulin, at concentrations observed in humans with pre-diabetes and used to treat individuals with diabetes mellitus type 2 (type 2 diabetes), inhibits low O2 tension-induced ATP release from human erythrocytes." (PMID 22934004, 2012). "• Many respondents found the question aiming to capture changes in diabetes-specific therapy (medication, insulin) in the previous 6 months either unclear or difficult." (PMID 22950744, 2012). "We validated our approach by demonstrating the functional relevance of a highly enriched module—“insulin regulation and diabetes”—by assessing glucose homeostasis and insulin resistance in sleep-fragmented mice." (PMID 22629440, 2012).
diabetes (continued). "In case a person with diabetes and active tuberculosis is poorly controlled on oral hypoglycemic agents, it is necessary to switch to insulin." (PMID 23497638, 2012). "The availability of an oral drug that can effectively counter insulin resistance, a crucial pathophysiological component of diabetes, has expanded our treatment options." (PMID 22577575, 2012). "Years that precede the development of T2DM are characterized by a progressive decline in both insulin action and defects in the early phase of the insulin secretion, with losses of postprandial glucose regulation occurring before overt diabetes." (PMID 22780564, 2012). "Other parameters should be available for surgical intervention: diabetes disease duration, medical therapy (oral hypoglycemic versus insulin), and pancreatic insulin reserve." (PMID 23133447, 2012). "Diabetes mellitus (DM) is a metabolic disorder characterized by an impairment of carbohydrate, fat, and protein metabolism caused by either lack of insulin secretion or decreased sensitivity of the tissues to insulin." (PMID 22474420, 2012). "22/50 patients (44%) discontinued anti-diabetes medications (14 sulfonylureas [36%], 7 insulin [23%], 4 sitagliptin [19%])." (PMID 22384240, 2012). "The effects of CTS involve reversal of diabetes-related dysfunction of insulin signaling, down-regulation of VEGF/PDGF signaling systems, and neurodegeneration of central cholinergic systems." (PMID 23082896, 2012). "In this report we document the first case of allergy to metacresol in the pediatric diabetes literature; metacresol is an excipient common to all currently available insulin preparations." (PMID 22937994, 2012). "Most obese individuals are insulin resistant, which is an important etiological factor for type 2 diabetes mellitus." (PMID 22110480, 2012). "This phenotypic spectrum of diabetes has also been reported in carriers of a mutation in ABCC8 or in the insulin (INS) gene, which both represent, with KCNJ11, the most frequently mutated genes in patients with NDM." (PMID 22701567, 2012). "Further study of these mechanisms, and the pathophysiological role for SUMOylation, will provide a new layer to our insight into insulin secretion in health and diabetes." (PMID 24970137, 2012). "Both groups were well matched for gender (majority male), NYHA class, and use of guideline validated therapies i.e. renin angiotensin system inhibitors, diuretics, spironolactone and diabetes treatment (diet, oral hypoglycaemics and/or insulin)." (PMID 22330091, 2012). "A 10-year follow-up of the UK Prospective Diabetes Study (UKPDS) did show beneficial effects of treatment with sulfonylurea and insulin on CVD and deaths from any cause." (PMID 22720085, 2012). "The increasing temporal resolution of the monitoring technology enabled increasingly intensive diabetes treatment, from daily insulin injections or oral medication, through insulin pump therapy, to the artificial pancreas." (PMID 24278682, 2012). "While the flexible intensive insulin treatment approach taught on DAFNE courses was seen as a logical and effective way of managing one’s diabetes, it was also considered more technically complex than other insulin regimens." (PMID 22891794, 2012). "These guidelines are followed and directly implemented by the Inpatient Diabetes consultative service, which serves to centralize direction of the insulin therapy during the postoperative period." (PMID 23209941, 2012). "IGR is also known as intermediate hyperglycemia or pre-diabetes and characterized by high blood glucose concentrations, insulin resistance and impaired insulin secretion." (PMID 23226241, 2012). "The group with higher baseline HbA1c was significantly younger, had fewer men, longer diabetes duration, higher BMI, more smokers, and was more often treated with insulin at the start of follow-up." (PMID 22719946, 2012).